VEGFC (vascular endothelial growth factor C)
Diseases named in the same sentence as VEGFC in open-access papers (continued):
Sharing a sentence is not in itself a finding about the gene and the disease.
tumor (continued). "Previous studies report that VEGFA, VEGFC and VEGFD play roles in tumor metastasis by promoting tumor lymphangiogenesis or angiogenesis and further promoting LN metastasis." (PMID 40693467, 2025). "VEGFC-VEGFCR3 and VEGFD-VEGFR3 signaling pathways are considered to be major drivers of tumor lymphangiogenesis and lymphatic remodeling." (PMID 39866224, 2025). "Consistent results were obtained for another TKI‐resistant sample showing VEGFA overexpression in tumor cell types and mutual exclusiveness of VEGFA and VEGFC." (PMID 40843133, 2025). "Lymphangiogenesis, orchestrated by the VEGFC-VEGFR-3 axis and often mediated by immune cells like macrophages in the tumor microenvironment, is a pivotal step in lymphatic metastasis." (PMID 41333209, 2025). "VEGFC, by binding to VEGFR-3, is a potent inducer of lymphangiogenesis, creating pathways for tumor cell dissemination." (PMID 41333209, 2025). "This inflammatory response is part of a broader tumor-induced immune disruption, which also includes enhanced lymphangiogenesis and lymphatic remodeling, driven by VEGFC and VEGFD, facilitating tumor dissemination." (PMID 40563651, 2025). "After the SH intervention, the levels of the tumor angiogenesis-related genes MMP-2, VEGFA, VEGFC, VAV2, and LARP1 were significantly downregulated when compared with the Model group, whereas the GADD45A level was markedly upregulated." (PMID 41444284, 2025). "The VEGF protein family consists of VEGFA, VEGFB, VEGFC, VEGFD, and many others, some members of which are inducers of tumor lymphangiogenesis." (PMID 39866224, 2025). "Here, we show marked increase in VE-cadherin fragmentation indicative of increased VE-cadherin dynamics in initial lymphatic vessels in the ear dermis in the presence of a tumor and in response to VEGFA or VEGFC treatment." (PMID 38148112, 2024). "Specifically, the expression levels of tumor proliferation and angiogenesis protein CCND1 and VEGFC were upregulated by STOML2 overexpression." (PMID 38214751, 2024). "The expression of RSPO3, ALPP, VEGFC, ANXA8, HES2, GLP2R, and KRT14 in normal tissues was significantly higher than that in tumor tissues." (PMID 38240936, 2024). "TAMs can promote carcinogenesis in cSCC by releasing cytokines, including vascular endothelial growth factor-C (VEGF-C) and matrix metalloproteinase (MMP) 9 and 11, which stimulate lymph-angiogenesis and tumor growth." (PMID 37887285, 2023). "A consistently high expression of VEGFC in stromal, immune, and ESTIMATE scores indicated lower tumor purity." (PMID 37852616, 2023). "Similar to the results at the cellular level, here we found that mRNA nano-lantern promoted the expression of Smad4 protein in tumor tissues and induced the decline of MYC, VEGFC, and CXCL5." (PMID 36894556, 2023). "Many malignant tumors secrete lymphangiogenic factors, such as VEGFC and VEGFD, and promote lymphangiogenesis in adjacent tissues, thereby helping tumor cells metastasize through lymph nodes." (PMID 37762426, 2023). "Secretion of VEGFC can induce lymphangiogenesis, while increased CCL5 in tumor microenvironment can form a concentration gradient to recruit M2 TAM, then promote TNF‐α secretion to increase lymphatic permeability." (PMID 37409440, 2023). "To further analyze the mechanisms of the tumor inhibition ability of mRNA nano-lantern, we evaluated the expression level of Smad4, downstream transcriptional regulatory genes, MYC, VEGFC, and CXCL5 in tumor tissues by Western blot." (PMID 36894556, 2023). "Across tumor stages, VEGFA, VEGFC, and PGF exhibited an increasing expression tendency as the tumor stage advanced." (PMID 37852616, 2023). "In the present study, histidine supplementation in HCC cells reduced the expression of tumor markers related to glycolysis (GLUT1 and HK2), inflammation (pSTAT3), angiogenesis (VEGFB and VEGFC), stem cells (CD133), metastasis (Snail/slug), and cell migration." (PMID 35267513, 2022).
tumor (continued). "Their established VEGF-C-mRNA (lymphangiogenesis-promoting factor, Vascular Endothelial Growth Factor C (VEGF-C), using AAV9 and mRNA delivery vectors) can increase the activation of tumor-specific T cells and their tumor infiltration in lymph nodes." (PMID 35204029, 2022). "Expression of VEGFC and PGF was highly correlated with the expression of endothelial markers in tumor samples, including CD31, CD34, and ENG (endoglin, a co-receptor for TGFβ)." (PMID 35600354, 2022). "Studies on animal models of cancer progression have reported that tumor cells secrete lymphangiogenic factors, including VEGFA, VEGFC, and VEGFD; induce active metastasis; and promote the circulation of cancer cells into LNs and other sites." (PMID 35626729, 2022). "Remarkably, we found that exogenous histidine treatment induced a reduction in the expression of tumor markers related to glycolysis (GLUT1 and HK2), inflammation (STAT3), angiogenesis (VEGFB and VEGFC), and stem cells (CD133)." (PMID 35267513, 2022). "VEGFR3 is also expressed on tumor lymphocytic vessels and when VEGFC, often secreted by the tumor, binds to it, LECs produce chemokines that attract TAMS into the tumor environment." (PMID 35681695, 2022). "Nine genes were upregulated in tumor tissues, while the PRKCD, RPS6KA1, CAT, and VEGFC genes were downregulated." (PMID 36254009, 2022). "Most studies have reported that VEGFR3 signaling in tumor cells depends on the VEGFC/VEGFR3 axis in an autocrine manner and mainly contributes to tumor invasion and metastasis." (PMID 36336681, 2022). "VEGFC can upregulate the expression of CCL21 in lymphatic vessels, driving tumor cells to express CCR7, and enhance the invasive phenotype of tumor cells." (PMID 34552874, 2021). "microRNA (miR)-27b acts as a potential tumour suppressor in GC and targets VEGFC expression, while miR-101 promotes cisplatin (DPP)-induced apoptosis partly via its targeting of VEGFC in DDP-resistant GC cells." (PMID 33407483, 2021). "We thus questioned classical activators of VEGFR3 such as VEGFC and VEGFD, which can be secreted by aggressive tumor cells and play key roles in neolymphangiogenesis in cancer." (PMID 34762341, 2021). "Although NRPa-308 represents an interesting hit if tumor cells express both NRPs and their ligands VEGFA/VEGFC, specific drugs targeting NRP1 should be more appropriate if only NRP1/VEGFA is present." (PMID 33461580, 2021). "Several papers showed that tumor cells aberrantly over-express VEGF and VEGFC and their receptors (VEGFR1, VEGFR2), creating autocrine proliferation loops." (PMID 34067671, 2021). "Some receptor tyrosine kinase inhibitors, such as gefitinib, afatinib, and anlotinib, can target the VEGFC-VEGFR3 signaling pathway, which potentially inhibits tumor-related lymphangiogenesis, lymphatic metastasis, and distant organ metastasis." (PMID 34552874, 2021). "We also observed significantly reduced levels of VEGFC, p-Akt and p-ERK proteins in the xenograft tumor tissues from the agomiR-944 group compared to those from the agomiR-NC group." (PMID 34233294, 2021). "HIFs are key players in tumor aggressiveness and drug resistance particularly through Vascular Endothelial Growth Factor-A (VEGFA)-dependent angiogenesis and VEGFC-dependent lymphangiogenesis." (PMID 33461580, 2021). "Vascular endothelial growth factor C (VEGFC), an activator of lymphangiogenesis, is newly identified as an immunomodulator which can regulate the immune system so that tumor cells more easily escape immune surveillance." (PMID 32154654, 2020). "In this study, we clearly show that overexpression of CCBE1 in CRC cells promotes VEGFC proteolysis and activation and that CCBE1 enhances tumor lymphangiogenesis and lymphatic metastasis in CRC." (PMID 32089745, 2020). "Based on the role of CCBE1 in VEGFC activation, it is rational that CCBE1 plays an oncogenic role, enhancing tumor lymphangiogenesis and lymphatic metastasis." (PMID 32089745, 2020).
tumor (continued). "Using the TCGA database, we analysed MAP3K8, CCL20, VEGFC, and ANGPTL4 gene expression levels in both normal tissue and tumour tissue samples." (PMID 32019546, 2020). "Afatinib inhibited LYVE-1, VEGFR2, VEGFR3, VEGFC, VEGF, and CCR7 expression in a dose-dependent manner in HCC827 xenograft tumour tissues, and these results demonstrated the anti-lymphangiogenic action of Afatinib." (PMID 31892990, 2020). "Using total protein from HCC827 xenograft tumour tissues, we found that Afatinib inhibited the phosphorylation of JAK1,2, STAT3, and FAK, the protein expression of LYVE-1, VEGFR2, VEGFR3, VEGFC, VEGFA, and CCR7." (PMID 31892990, 2020). "We have previously measured lymphangiogenesis markers VEGFC and LYVE-1 expression in these tumour samples." (PMID 31277414, 2019). "Vascular endothelial growth factors with their receptors (VEGFC/A, VEGFR-1/3) have been characterized as essential lymphangiogenic factors, but research also showed their important role in angiogenesis and tumor progression via blood vessels." (PMID 31717665, 2019). "Finally, we demonstrated that PROX1 and other vascular factors, such as VEGFC (vascular endothelial growth factor C), BAIAP2 (BAI1 associated protein 2), FGF2 (fibroblast growth factor 2), and PLAT (plasminogen activator) are differently expressed in FTC human tissues compared to non-tumor tissues." (PMID 31717665, 2019). "Docetaxel caused an upregulation in pro-lymphangiogenic factors including VEGFC and TNF-α in the tumor microenvironment in vivo." (PMID 29976154, 2018). "However, it remains unknown how the generation and secretion of SDF1/CXCR4 molecules correlate in the same cancer cell and how they interact with upstream and downstream pathways, e.g., AnnexinA7 and VEGFC/D-VEGFR3/NRP2 during tumor development and progression." (PMID 29783989, 2018). "Vascular endothelial growth factor C (VEGF-C) and vascular endothelial growth factor D (VEGF-D) can also increase the vascular permeability of tumor cells and change the adhesive properties of the lymphatic endothelium." (PMID 30564284, 2018). "Together, these findings show docetaxel increases expression of multiple pro-lymphangiogenic factors, including VEGFC and TNF-α, in the 4T1 tumor microenvironment, and these changes can be mitigated by the addition of anti-VEGFR3 therapy." (PMID 29976154, 2018). "The molecular mechanism involved in the tumor metastasis to SLN remains relatively poorly understood, but it has been proved that the expression of vascular endothelial growth factor C (VEGF-C) is a potential pathogenesis." (PMID 28667103, 2017). "It has been indicated that VEGFC or VEGFD can specifically bind vascular endothelial growth factor receptor-3 (VEGFR-3), as well as promote tumor lymphangiogenesis and prevent the spread of lymphatic tumor to regional lymph nodes." (PMID 27145366, 2016). "Neuropilin-2 (Nrp2) is a well known receptor for the vascular endothelial growth factor-C (VEGF-C) and activates lymph nodes as well as promotes tumor metastasis by lymphangiogenesis." (PMID 27766950, 2016). "Vascular endothelial growth factor-C (VEGF-C) is the chief lymphangiogenic mediator, and makes crucial contributions to tumor lymphangiogenesis." (PMID 27345723, 2016). "VEGF family members, including VEGFA, VEGFB, VEGFC, and VEGFD, are secreted by autocrine stimulation of tumor cells as well as through paracrine influences of the proangiogenic tumour microenvironment." (PMID 25810565, 2015). "These genes included tumor markers (MUC16), genes that control tumor migration (MYL9), metastasis (CEACAM6, VEGFC, CX3CL1, CST1, CCL5, S100A9, IGF1, NOTCH3), cell adhesion (FN1, CEACAM1), and inflammation (TRAF2, NF-κB2 and RelB)." (PMID 26090868, 2015). "We confirmed that vascular endothelial growth factor C (VEGFC), which plays a role in tumor progression, is a novel target of miR-27b." (PMID 23593282, 2013).
tumor (continued). "Supportive of the importance of NF-κB signaling in the pathogenesis of this tumor was our finding that 4 NF-κB target genes, IL-11, CXCL5, VEGFC, and CCL20, are on the list of strongly expressed genes from our gene expression profiling analysis." (PMID 24223206, 2013). "We identified vascular endothelial growth factor C (VEGFC) as a novel target gene of miR-27b and determined that miR-27b functioned as an inhibitor of tumor progression and angiogenesis through targeting VEGFC in CRC." (PMID 23593282, 2013). "Vascular endothelial growth factor C (VEGF-C) and its receptors VEGFR3 and VEGFR2 have a central role in regulation of the development and function of the lymphatic system as well as in tumor lymphangiogenesis." (PMID 19821979, 2009). "The expression of VEGF-C (Vascular Endothelial Growth Factor – C), its receptor VEGFR-3 and CD44, were studied on feline mammary samples to assess the importance of lymphangiogenesis and lymphangiotrophism in neoplasia." (PMID 17222331, 2007). "Vascular endothelial growth factor-C has been detected in many human cancers, and a number of reports have shown a correlation between VEGF-C expression in human tumours and the formation of metastases in regional lymph nodes." (PMID 17164762, 2007). "Vascular endothelial growth factor-C and VEGF-D have been shown to promote tumour lymphangiogenesis, the metastatic spread of tumour cells to lymph nodes and, in some cases, distant organ metastasis in multiple animal models of cancer." (PMID 16641900, 2006). "VEGFC was reduced in PALNs of SA-HFIRE mice with little difference between day 1 and day 3, reflective of decreased VEGFC gene expression within the tumor." (PMID 39998766, 2025). "Additionally, vascular endothelial growth factor C (VEGFC) is used in combination to induce functional lymphangiogenesis, aiding dendritic cell (DC) migration of tumor‐draining lymph nodes (TDLNs)." (PMID 40917034, 2025). "Although during inflammatory lymphatic remodeling the production of VEGFA and VEGFC is expected by activated macrophages, there was no observable increase of either within the treated tumor." (PMID 39998766, 2025). "Anti‐VEGFC antibody treatment inhibited the growth of experimental tumours in nude mice derived from control as well as multi‐irradiated X‐ and P‐irradiated MDAMB231 cells, with some tumours exhibiting near‐complete regression." (PMID 40400121, 2025). "In the SWI/SNF-mutant cohort, a seven-gene signature comprising CRIM1 (angiogenesis), VEGFC (lymphangiogenesis), BMP7 (tumor microenvironment regulation), NR1D2 (immune modulation), BMPR1B (tumor proliferation), CR2 (B-cell activation), and TAPBPL (antigen presentation) was ultimately retained." (PMID 41438758, 2025). "Furthermore, upon treating various types of tumour cell lines with FOXO1 inhibitors, we observed not only the upregulation of VEGFC, PD‐L1 and CCL4 but also varying degrees of increase in MOMP‐related molecules (such as BAX, BAK1, CASP3, STING, IRF3 and RELB)." (PMID 38899748, 2024). "Activation of VEGFC/VEGFR3 signaling in lymphatic endothelial cells (LECs) increases the proliferation of LECs and the formation of lymphatic vessels, leading to the increase of lymphatic metastasis of tumor cells." (PMID 38426109, 2024). "We hypothesized that the zippering of dermal lymphatic junctions and the shape shift of VE-cadherin fragments in the tumor periphery may be related to production of VEGFA and/or VEGFC, which both bind to VEGFR2, in the tumor microenvironment." (PMID 38148112, 2024). "PGE2 and prostaglandin E2 receptor EP4 (EP4) subtype combine on multiple cell types: tumor cells, tumor-infiltrating immune cells, and lymphatic endothelial cells (LECs), EP4 activation on cancer cells, and macrophages upregulated vascular endothelial growth factor c/d (VEGF-C/D) production." (PMID 38549934, 2024).
tumor (continued). "Based on the results of 170 DEGs significantly enriched for functions and pathways, activation of Akt promote tumor LYM with metastasis, the hypoxic microenvironment created favorable conditions for tumor LYM, and IL-17 promoted LYM by facilitating VEGFC secretion." (PMID 38638428, 2024). "In the human PDAC patient tumor transcriptome (TCGA), we identify strong and significant correlations between tumoral GHR expression and known lymphangiogenic (LYVE1, FLT4, VEGFC, and PDPN) and angiogenic (PDGFRa, FGFR1, TGFB3, TGFB1, TGFBR2, HIF1a, IL6, and IL1B) markers." (PMID 39000545, 2024). "In addition, in colorectal cancer, the VEGFC/VEGFR3 pathway can induce the proliferation of LECs and macrophages, and VEGFR3 can also induce TAM polarization to M2 type to participate in tumor immunosuppression." (PMID 37803421, 2023). "Enrichment of VEGFC in the GC microenvironment could induce lymphangiogenesis, while increased CCL5 in tumor microenvironment could form a concentration gradient to recruit M2 type TAM, then promote TNF‐α secretion to increase lymphatic permeability." (PMID 37409440, 2023). "Finally, the results of this study highlighted the role played by exosomes in the transport and diffusion into the tumor microenvironment of some of the factors overexpressed in resistant cells, such as VEGFA, VEGFC, Ang2 and P-gp." (PMID 36874116, 2023). "Furthermore, the increased protein level of VEGFC and BCL2 as well as reduced cell apoptosis caused by depletion of UTX could be rescued by ectopic expression of EMP1, suggesting that EMP1 is a significant effector gene mediating the tumor-suppressing function of UTX in CRC." (PMID 37679762, 2023). "Secretion of VEGFC and CCL5 mediated by CRIP1 and CREB1 could reshape the tumor microenvironment into a suitable “soil” which could favor lymphangiogenesis and LM." (PMID 37409440, 2023). "In KIRP, VEGFA, VEGFC, and PGF were differentially expressed across tumor stages." (PMID 37852616, 2023). "CRIP1 and CREB1 mediated secretion of VEGFC and CCL5 could then reshape the tumor microenvironment into a suitable “soil” which favor lymphangiogenesis and LM in GC." (PMID 37409440, 2023). "In resistant cells, the overall effect of the PTX-Elacridar combined treatment was inhibitory of tumor growth, nevertheless these combined drugs determined a nuclear accumulation of TUBβIII, as well as the induction of pro-angiogenic genes (VEGFA, VEGFC, Ang2)." (PMID 36874116, 2023). "Of these genes, ITGA5, PLAU, PLAUR, SERPINE1, TGFB1, and VEGFC were significantly highly expressed in tumor compared to normal tissues." (PMID 36425786, 2022). "In addition, vascular endothelial growth factor C (VEGF-C) and its receptor VEGFR-3 also promote tumor lymphangiogenesis by activating the related signaling pathways." (PMID 36261482, 2022). "Therefore, these six tumor-related genes (ITGA5, PLAU, PLAUR, SERPINE1, TGFB1, and VEGFC) were considered as prognostic biomarkers for HNSCC." (PMID 36425786, 2022). "In addition to VEGFC/D in the VEGF family, VEGFA has been found to be involved in tumor lymphangiogenesis." (PMID 34552874, 2021). "Tumor cells, can promote tumor lymphangiogenesis and lymph node metastasis by activating mechanisms through TGF-β to increase the expression of lymphangiogenic molecules as Vascular Endothelial Growth Factor C (VEGF-C) while direct effects of TGF-β on lymphangiogenesis is inhibitory." (PMID 34316330, 2021). "The VEGFC-VEGFR3 and VEGFD-VEGFR3 axes are considered the major drivers of tumor lymphangiogenesis." (PMID 32089745, 2020). "This infers that VEGFR2, but neither by NRP2 nor VEGFR3, relayed the negative control of VEGFC on tumor." (PMID 33067561, 2020). "Indeed, recently VEGFC and VEGFD have also been reported to regulate the inflammatory tumor microenvironment, which regulates early stages of tumor growth." (PMID 31069961, 2019). "We have also previously shown expression of CD31, VEGFC, and LYVE1 to be high in this tumour set." (PMID 31277414, 2019).